FLOT1 (flotillin 1)
Description:
May act as a scaffolding protein within caveolar membranes, functionally participating in formation of caveolae or caveolae-like vesicles.
Tractability: Antibody: UniProt places it where antibodies can reach, with high confidence; its Gene Ontology location is reachable by antibodies, with high confidence. PROTAC: ubiquitination databases record sites on it; its protein half-life has been measured.
Gene: Protein-coding gene on chromosome 6 (30,727,709 to 30,743,075, reverse strand). Ensembl gene ENSG00000137312.
Subcellular location: Cell membrane; Endosome; Membrane, caveola; Melanosome; Membrane raft
Subcellular location (Human Protein Atlas): Golgi apparatus; Plasma membrane; Vesicles
Pathways (Reactome):
Signal Transduction: RHOA GTPase cycle; RHOB GTPase cycle; RHOC GTPase cycle
Programmed Cell Death: RIPK1-mediated regulated necrosis; Regulation of necroptotic cell death
Neuronal System: Synaptic adhesion-like molecules
Gene Ontology:
Molecular function: protease binding; protein binding; ionotropic glutamate receptor binding
Biological process: adherens junction organization; caveola assembly; extracellular matrix disassembly; plasma membrane raft assembly; plasma membrane raft organization; positive regulation of canonical NF-kappaB signal transduction; positive regulation of endocytosis; protein localization to plasma membrane; regulation of neurotransmitter uptake; positive regulation of synaptic transmission, dopaminergic; regulation of receptor internalization; cell-cell adhesion mediated by cadherin; cell-cell junction assembly; intracellular signal transduction
Cellular component: adherens junction; apical plasma membrane; basolateral plasma membrane; cell-cell contact zone; cell-cell junction; centriolar satellite; COP9 signalosome; cortical actin cytoskeleton; cytoplasmic vesicle; dopaminergic synapse; early endosome; endosome; extracellular exosome; flotillin complex; focal adhesion; lamellipodium; lysosomal membrane; melanosome; membrane; membrane raft; microtubule organizing center; plasma membrane; uropod; caveola; external side of plasma membrane; and 7 more
Genetic constraint (gnomAD): Loss-of-function variants: 40 observed, 60.08 expected, observed/expected ratio (o/e) 0.67, 90% interval 0.52 to 0.87. The upper end of that interval is the gene's LOEUF score, 0.87, which puts it in group 3 of 6, group 1 being the genes least tolerant of losing a copy. Missense variants: 423 observed, 563.51 expected, observed/expected ratio (o/e) 0.75, 90% interval 0.69 to 0.81. Synonymous variants: 178 observed, 215.3 expected, observed/expected ratio (o/e) 0.83, 90% interval 0.73 to 0.94.
Homologues: Orthologues: chimpanzee FLOT1 (99% identical), pig FLOT1 (99% identical), rabbit FLOT1 (99% identical), macaque FLOT1 (98% identical), mouse Flot1 (98% identical), rat Flot1 (98% identical), dog FLOT1 (97% identical), guinea pig FLOT1 (97% identical), tropical clawed frog flot1 (81% identical), zebrafish flot1a (79% identical), zebrafish flot1b (78% identical), Drosophila melanogaster Flo1 (64% identical). Paralogues in human: FLOT2 (48% identical).
Diseases named in the same sentence as FLOT1 in open-access papers:
FLOT1 is named in the same sentence as 109 diseases in open-access papers, as found by Europe PMC text mining. Sharing a sentence is not in itself a finding about the gene and the disease. The quoted sentences say what the papers report.
breast carcinoma (35 papers, 2013 to 2025). "The FLOT1 has been implicated as being associated with a poor prognosis in breast cancer, colon cancer, esophageal squamous cell carcinoma cells, and many other cancers." (PMID 39404386, 2024). "Inhibition of Akt1/Foxo3a/p21/p27 was observed in breast cancer cells with Flot-1 knockdown, which was associated with an arrest of proliferation and tumorigenicity." (PMID 26206082, 2015). "Our study demonstrated that miR-124 acts as a tumor suppressor by directly targeting FLOT1 in breast cancer, which suggested that miR-124 has potential diagnostic and therapeutic value for breast cancer treatment." (PMID 24330780, 2013). "Consistent with the study above, we found that miR-124 could directly target and downregulate FLOT1, and high FLOT1 expression was associated with low miR-124 levels in breast cancer specimens." (PMID 24330780, 2013). "In breast cancer, inhibiting FLOT1 expression in breast cancer has been reported to be involved in the proliferation and tumorigenicity of breast cancer cells in vitro and in vivo." (PMID 40335491, 2025). "Flotillin-1 is overexpressed in numerous solid tumors, and its S-palmitoylation enhances its stability and metastatic potential in breast cancer cells and experimental metastasis models." (PMID 40066091, 2025). "FLOT1 has been reported in multiple types of cancers, including breast cancer, gastric cancer, hepatocellular carcinoma, and HNSCC." (PMID 40335491, 2025). "It has been observed that Flotillin-1 is overexpressed in numerous solid tumors, and its S-palmitoylation contributes to its stability and subsequent metastatic capabilities in breast cancer cells and experimental metastasis models." (PMID 38415253, 2024). "In a separate study, it was found that when flotillin-1 (FLOT1) was silenced using RNAi in breast cancer, FOXO3a was activated." (PMID 38505423, 2024). "Knockdown of Flotillin-1 impairs cell proliferation and tumorigenicity in breast cancer through upregulation of FOXO3a." (PMID 35990908, 2022). "Flotillin-1 is highly expressed in breast cancer specimens, and the high expression level of flotillin-1 is significantly correlated with later clinical staging and poorer patient survival." (PMID 31562347, 2019). "Flotillin-1 is highly expressed in breast cancer, and the high expression level of flotillin-1 is significantly correlated with poorer patient survival." (PMID 31562347, 2019). "For example, FLOT1 gene, an important promoter of breast cancer cell proliferation and migration, shows differential expression and differential methylation of both its enhancer and promoter between normal tissues and cancer tissues." (PMID 28621677, 2017). "The expression levels of FLOT1 in bladder and breast cancers were negatively correlated with the prognosis of patients." (PMID 28549468, 2017). "Flotillin-1 was generally over-expressed in breast cancer, colorectal cancer, liver cancer, esophageal squamous cell carcinoma and so on." (PMID 28881760, 2017). "Flotillin 1 (FLOT1) is documented in the literature to be implicated in cell migration and was a validated target of miR-124-3p in breast cancer." (PMID 26002553, 2015). "CAV1 and FLOT1 were also shown to affect migration and invasion in porcine kidney epithelial cells and breast cancer." (PMID 26002553, 2015). "In fact, flotillin-1 differential expression has been sporadically reported in pathologic conditions such as breast cancer, colorectal cancer, and esophageal squamous cell carcinoma." (PMID 25243186, 2014). "It has been reported that the silencing of FLOT1 inhibited the proliferation and tumorigenesis of breast cancer, oral squamous cell carcinoma and esophageal squamous cell carcinoma cells both in vitro and in vivo." (PMID 24886554, 2014). "Flotillin-1 is a raft protein that can co-localize with ER in lipid rafts from MCF-7 breast cancer cells, leading to modulation of cell growth." (PMID 24404144, 2014).
breast carcinoma (continued). "Flotillin-1 promotes tumorigenesis of various cancers, such as esophageal squamous cell carcinoma, non-small cell lung cancer and breast cancer." (PMID 24947166, 2014). "We have recently shown that in MCF7 breast cancer cells, flotillin-1 depletion results in a paradoxical up-regulation of EGFR expression due to the increased phosphatidyl-inositol 3-kinase (PI3K) signaling (; see Section 3 below)." (PMID 24709906, 2014). "Flotillin-1 promotes breast cancer carcinogenesis inducing entry into the S phase of the cell cycle and by upregulating the transcription factor Foxo3a." (PMID 24947166, 2014). "Recently, deregulation of flotillin-1 was found in epithelium-originated cancer, including breast cancer, colorectal cancer, and esophageal squamous cell carcinoma." (PMID 25243186, 2014). "Ectopic expression of FLOT1 promoted proliferation of esophageal squamous cell carcinoma cell lines, whereas silencing FLOT1 inhibited the proliferation and tumorigenicity of breast cancer cells both in vitro and in vivo." (PMID 23840303, 2013). "Consistent with the effect of miR-124, the knockdown of FLOT1 significantly inhibited breast cancer cell growth and migration." (PMID 24330780, 2013). "Recently, deregulation of FLOT1 was found in epithelium-originated cancer, including breast cancer, colorectal cancer, as well as esophageal squamous cell carcinoma." (PMID 23840303, 2013). "IHC was performed to detect FLOT1 expression in 5 normal breast tissues and 78 clinical breast cancer specimens, and the miR-124 expression levels were simultaneously analyzed by RT-PCR." (PMID 24330780, 2013). "Our study showed that miR-124 was downregulated in breast cancer, and a bioinformatic analysis predicted flotillin-1 (FLOT1) to be a potential target of miR-124." (PMID 24330780, 2013). "In breast cancer, the FLOT1 expression level correlated with clinical staging and prognosis, and its silencing inhibited the proliferation and tumorigenicity of breast cancer cells in vitro and vivo." (PMID 24330780, 2013). "In this study, we investigated the role of miR-124 in breast cancer and clarified the regulation of flotillin-1 (FLOT1) by miR-124." (PMID 24330780, 2013). "Our findings, consistent with other groups, indicated that the role of miR-124 in the growth and metastasis inhibition was accomplished by the regulation of FLOT1 in breast cancer." (PMID 24330780, 2013). "Furthermore, silencing FLOT1 inhibits proliferation and tumorigenicity in breast cancer cells by upregulating FOXO3a." (PMID 40335491, 2025). "The knockdown of FLOT1 impairs proliferation and migration in breast cancer." (PMID 39404386, 2024). "Upregulation of Flotillin-1 predicts poor prognosis and promotes malignant progression, proliferation and metastasis of multiple tumors, including non-small cell lung, breast cancer, renal cell carcinoma, neuroblastoma, bladder cancer, prostate cancer and hepatocellular carcinoma." (PMID 35990908, 2022). "Previous studies showed that FLOT1 was constantly overexpressed in various cancers such as colorectal tumor, esophageal squamous carcinoma, tongue squamous carcinoma, prostate cancer, bladder transitional cell carcinoma, renal cell carcinoma and breast cancer." (PMID 28549468, 2017). "Flotillin-1 has made effects with Akt/FOXO3a pathways in breast cancer." (PMID 28881760, 2017). "As for FLOT1 (flotillin-1), another gene verified by our ELISA test, its important roles in promoting tumorigenesis and progression of several cancers like non-small cell lung cancer, breast cancer and hepatocellular carcinoma have been recently reported." (PMID 27898717, 2016). "Indeed, silencing of FLOT1 induced G1-S-phase arrest of breast cancer cells due to upregulated expression of the CDK inhibitors p21Cip1 and p27Kip1." (PMID 26095524, 2015).
breast carcinoma (continued). "FLOT1, a putative target of miR-182-5p identified by TargetScan, was of particular interest because it had three high scoring predicted binding sites and was previously considered as a positive cell cycle regulator in breast cancer." (PMID 24886554, 2014). "However, in breast cancer cells with mutant PIK3CA, a well-known downstream target of EGFR signaling, knockdown of flotillin-1 causes an upregulation of EGFR and hyperactivation of MAPK signaling." (PMID 25180832, 2014). "Moreover, FLOT1 was widely upregulated, and inversely correlated with miR-124 in breast cancer tissues." (PMID 24330780, 2013). "FLOT1 is overexpressed in several types of cancer, including breast cancer." (PMID 24330780, 2013). "Our study demonstrated that miR-124 might be a tumor suppressor in breast cancer via the regulation of FLOT1." (PMID 24330780, 2013). "Therefore, FLOT1 has an important role in the proliferation and invasion of breast cancer cells, which was regulated by miR-124." (PMID 24330780, 2013). "Furthermore, we validated FLOT1, which was overexpressed in breast cancer and predicted as the target of miR-124, by 3′-UTR luciferase assays and western blot analysis." (PMID 24330780, 2013). "Therefore, we concluded that miR-124 inhibited FLOT1 expression by binding to the 3′-UTR sequences of FLOT1 in breast cancer." (PMID 24330780, 2013). "Furthermore, a Matrigel invasion assay indicated that the knockdown of FLOT1 inhibited the invasion of breast cancer cells, an effect that resembled the inhibitory effect of miR-124 in breast cancer cells." (PMID 24330780, 2013). "It has been reported that FLOT1 was a regulator of ErbB2 in breast cancer." (PMID 23840303, 2013). "We performed a luciferase reporter assay to determine whether FLOT1 is a direct target of miR-124 in breast cancer cells." (PMID 24330780, 2013). "In addition, silencing FLOT1 inhibited the proliferation and tumorigenesis of breast cancer cells both in vitro and in vivo, through inhibition of FOXO3a." (PMID 23840303, 2013). "The knockdown of FLOT1 reportedly suppressed the proliferation and tumorigenesis of breast cancer cells by enhancing the transcriptional activity of FOXO3a, inhibiting Akt activity, downregulating cyclin D1 and upregulating the cyclin-dependent kinase inhibitors p21Cip1 and p27Kip1." (PMID 24330780, 2013). "Consequently, targeting the S-palmitoylation of flotillin-1 may represent a viable strategy to combat breast cancer metastasis." (PMID 40066091, 2025). "Therefore, targeting flotillin-1 S-palmitoylation could be a promising approach for addressing breast cancer metastasis." (PMID 38415253, 2024). "Also, the enhancer methylation correlates with FLOT1 expression much better than promoter methylation (t-test:p < 0.05), suggesting the upregulation of FLOT1 in breast cancer, as observed in many other genes as well, is dominated by the activation of its enhancer." (PMID 28621677, 2017). "Further in vitro experiments proved that the down-regulation of FLOT1 in renal and breast cancers could inhibit the proliferation of cancer cells via activating AKT/FOXO3a signaling pathway, which is consistent with the results of our study in bladder cancer cells." (PMID 28549468, 2017). "Moreover, in breast cancer, esophageal squamous cell carcinoma, hepatocellular carcinoma, and lung adenocarcinoma, overexpression of FLOT1 could be used as a valuable maker for the prediction of a poor prognosis for patients." (PMID 24886554, 2014). "Finally, knockdown of FLOT1 consistent with the effects of miR-124 in breast cancer, and rescue expression of FLOT1 could partially restore these miR-124 effects." (PMID 24330780, 2013). "Moreover, in breast cancer and esophageal squamous cell carcinoma, overexpression of FLOT1 could be used as a valuable maker for prediction of poor prognosis of patients." (PMID 23840303, 2013).
breast carcinoma (continued). "Western blot analysis show that EpCAM-positive breast cancer exosomes express AnxA2 and exosomal markers CD9, TSG101, and flotillin-1." (PMID 31992335, 2020). "Knockdown of either flotillin-1 or -2 inhibits the proliferation and invasiveness of MCF-7 and MDA-MB-231 human breast cancer cells." (PMID 31562347, 2019). "It has been reported that FLOT1 was the upstream regulator of AKT/FOXO3a pathway in renal cell cancer and the proliferation regulator in BCa and breast cancer." (PMID 28549468, 2017). "To study the function of flotillins in breast cancer cells, we generated human MCF7 cell lines in which flotillin-1 or flotillin-2 expression was stably knocked down by means of lentivirus mediated short hairpin RNAs (shRNAs)." (PMID 24304721, 2013). "Furthermore, miR-485-5p was shown to suppress esophageal squamous cell carcinoma (ESCC) progression by inhibiting flotillin-1 expression leading to reduced EMT process, and target PGC-1α to inhibit breast cancer cell metastasis." (PMID 34856993, 2021). "In an ErbB2 overexpressing breast cancer cell line, SKBR3, flotillin-1 and flotillin-2 partially colocalized with ErbB2 at the plasma membrane and formed a complex with ErbB2 and Hsp90 which is an important factor for the stabilization of ErbB2 at the plasma membrane." (PMID 24709906, 2014). "In the SKBR3 breast cancer cells, the result that Akt phosphorylation is reduced upon depletion of flotillin-2, but not after flotillin-1 knockdown, agreed with our data." (PMID 23658725, 2013). "However, another study suggested that flotillin-2 but not flotillin-1 expression can be used as a prognostic marker for relapse in breast cancer in patients of stage I/II." (PMID 24709906, 2014). "To test whether FLOT1 is the direct functional mediator of the miR-124 induced inhibition of breast cancer cell proliferation and migration, we co-transfected miR-124 mimics along with wt/mut 3′-UTR-FLOT1 plasmid which FLOT1 cDNA contained wild type or mutant 3′ UTR into breast cancer cells." (PMID 24330780, 2013).
esophageal squamous cell carcinoma (14 papers, 2013 to 2025). Esophageal squamous cell carcinoma (ESCC) is a type of esophageal carcinoma (EC) that can affect any part of the esophagus, but is usually located in the upper or middle third. "In contrast, overexpression of FLOT1 increased cell proliferation, anchorage-independent growth, and invasive ability through activation of NF-κB signaling in esophageal squamous cell carcinoma cells." (PMID 23840303, 2013). "The lipid raft protein FLOT1 is upregulated in esophageal squamous cell carcinoma (ESCC) samples from patients, and it has been shown that FLOT1 promotes ESCC cell proliferation and tumor growth in mice." (PMID 39996775, 2025). "The lipid raft protein FLOT1 is up-regulated in esophageal squamous cell carcinoma (ESCC) cell lines and samples from patients and promotes ESCC cell proliferation and tumor growth in mice." (PMID 27181092, 2016). "Recently, miR-138 was reported to be down-regulated in esophageal squamous cell carcinoma (ESCC) and the markers of lipid rafts FLOT1, FLOT2 and caveolin-1 were identified as its targets, and NF-kappaB was activated." (PMID 24204780, 2013). "Additionally, miR-138 was also reported to regulate FLOT1 in esophageal squamous cell carcinoma." (PMID 24330780, 2013). "However it is found that FLOT1 can activate tumor necrosis factor-alpha (TNF-α) receptor signaling and sustain activation of NF-kappa B in esophageal squamous cell carcinoma cells." (PMID 27898717, 2016).